TACR3 (tachykinin receptor 3)
Description:
Receptor for the tachykinin neuromedin-K (neurokinin B), also able to bind and respond to tachynins substance K/neurokinin A and substance P. The rank order of affinity of this receptor to tachykinins is: neuromedin-K > substance K and substance P. Neuromedin-K binding to its receptor triggers G protein-coupled receptor signaling via activation of G(q) and phosphatidylinositol hydrolysis by phospholipase C. Neuromedin-K binding also triggers signaling via activation of adenylate cyclase activity which results in increased intracellular levels of cyclic AMP (cAMP) (By similarity).
Synonyms: NKR; NK-3R; NK3R; TAC3R; HH11; NK3; TAC3RL
Tractability: Small molecule: an approved drug acts on it; a high-quality ligand is known; it belongs to a druggable protein family. Antibody: its Gene Ontology location is reachable by antibodies, with high confidence; UniProt places it where antibodies can reach, with medium confidence; UniProt predicts a signal peptide or a membrane-spanning region. PROTAC: a small molecule that binds it is known.
Target class: Membrane receptor; Short peptide receptor (family A GPCR); Neurokinin receptor; Family A G protein-coupled receptor; Peptide receptor (family A GPCR)
Chemical probes: CHEMBL3422010, PD-160946, PD-161182, PD083476, PD084696, PD157672 (high quality), TALNETANT (high quality)
Safety:
Unwanted effects reported when the protein is acted on. In parentheses: how it was acted on, where the effect was seen, and who reports it.
Contraction of gastric smooth muscle and ileum (activation; gastrointestinal; source: Brennan et al. (2024))
opioid dependence (source: ClinPGx)
Gene: Protein-coding gene on chromosome 4 (103,586,031 to 103,719,985, reverse strand). Ensembl gene ENSG00000169836.
Subcellular location: Cell membrane
Pathways (Reactome):
Signal Transduction: G alpha (q) signalling events; Tachykinin receptors bind tachykinins
Gene Ontology:
Molecular function: neuromedin K receptor activity; protein binding; tachykinin receptor activity; G protein-coupled peptide receptor activity; G protein-coupled receptor activity
Biological process: phospholipase C-activating tachykinin receptor signaling pathway; positive regulation of flagellated sperm motility; adenylate cyclase-activating G protein-coupled receptor signaling pathway; tachykinin receptor signaling pathway; conditioned place preference; drinking behavior; G protein-coupled receptor signaling pathway; neuropeptide signaling pathway; positive regulation of blood pressure; positive regulation of heart rate; positive regulation of luteinizing hormone secretion; positive regulation of uterine smooth muscle contraction; regulation of dopamine metabolic process; regulation of feeding behavior; response to cocaine; response to estradiol; vagina development
Cellular component: plasma membrane; sperm midpiece; axon terminus; cell periphery; dendrite membrane; dendritic spine head; dendritic spine membrane; membrane; neuronal cell body; neuronal cell body membrane
Genetic constraint (gnomAD): Loss-of-function variants: 37 observed, 40.23 expected, observed/expected ratio (o/e) 0.92, 90% interval 0.71 to 1.21. The upper end of that interval is the gene's LOEUF score, 1.21, which puts it in group 5 of 6, group 1 being the genes least tolerant of losing a copy. Missense variants: 558 observed, 626.51 expected, observed/expected ratio (o/e) 0.89, 90% interval 0.83 to 0.95. Synonymous variants: 233 observed, 236.85 expected, observed/expected ratio (o/e) 0.98, 90% interval 0.88 to 1.1.
Homologues: Orthologues: chimpanzee TACR3 (99% identical), macaque TACR3 (98% identical), rabbit TACR3 (92% identical), pig TACR3 (90% identical), dog TACR3 (88% identical), rat Tacr3 (86% identical), mouse Tacr3 (86% identical), guinea pig TACR3 (74% identical), tropical clawed frog tacr3 (69% identical), zebrafish tacr3l (57% identical), zebrafish tacr3a (55% identical), Caenorhabditis elegans tkr-1 (26% identical). Paralogues in human: TACR1 (51% identical), TACR2 (43% identical), NPY1R (23% identical), GPR83 (22% identical), NPY2R (21% identical), PRLHR (20% identical), NPY4R (19% identical), NPY4R2 (19% identical), GPR75 (18% identical), MTNR1A (18% identical), PROKR2 (17% identical), MTNR1B (16% identical), and 21 more.
Diseases named in the same sentence as TACR3 in open-access papers:
TACR3 is named in the same sentence as 56 diseases in open-access papers, as found by Europe PMC text mining. Sharing a sentence is not in itself a finding about the gene and the disease. The quoted sentences say what the papers report.
hypogonadotropic hypogonadism (24 papers, 2011 to 2025). Abnormal ovarian or testicular function due to insufficient hormonal stimulation from the hypothalamic-pituitary axis. "It is known that mutations in the TAC3 or TACR3 genes, respectively coding for NKB or NK3R, cause hypogonadotropic hypogonadism in humans because of disturbances in the secretion of gonadotropic hormones from the anterior pituitary gland." (PMID 40552024, 2025). "In humans, TACR3 resides on the autosome, encodes receptors for neurokinin B, and is associated with hypogonadotropic hypogonadism." (PMID 39778707, 2025). "The gene TACR3 plays a key role in reproductive functions, and loss-of-function mutations in this gene can lead to hypogonadotropic hypogonadism and infertility in humans." (PMID 39071778, 2024). "Mutations in the TAC3 or TACR3 genes encoding for NKB and its receptor NK3R, respectively, lead to hypogonadotropic hypogonadism and infertility in humans." (PMID 25713511, 2015). "Loss-of-function mutations of Tac3 and Tacr3, which encode NKB and NK3R, respectively, have been identified in patients with hypogonadotropic hypogonadism." (PMID 25362998, 2014). "All these data strongly suggest that the gonadotrope deficiency in subjects with TAC3/TACR3 mutations is linked to a slowing of the frequency of endogenous GnRH secretion." (PMID 22031817, 2011). "Importantly, inactivating mutations of the TAC3 or TACR3 (encoding the NK3 receptor) gene lead to hypogonadotropic hypogonadism in humans, suggesting the importance of neurokinin B-NK3R signaling in human reproduction." (PMID 34566891, 2021). "Loss-of-function mutations in the genes encoding for kisspeptin (Kiss1) or its receptor (Kiss1r) or NKB (encoded by the Tac2 gene) and its receptor (NK3R, encoded by the Tacr3 gene) in humans and mice, are linked to hypogonadotropic-hypogonadism and infertility." (PMID 30565563, 2018). "The role of TACR3 activation in reproductive functions has aroused a lot of interest in the reproductive biology field mainly due to the recent demonstrations that loss-of-function mutations in TACR3 or its ligand NKB can lead to hypogonadotropic hypogonadism and infertility in human." (PMID 31412674, 2019). "Dissociated central hypogonadism, with low LH and normal FSH, has been described in individuals with TACR3 pathogenic variants." (PMID 35722485, 2022). "NKB, encoded by the TAC3 gene in humans and Tac2 gene in rodents, acts via the NKB receptor (NK3R; encoded by TACR3 gene in humans and Tacr3 in rodents), and mutations in either TAC3 or TACR3 are associated with hypogonadotropic hypogonadism." (PMID 31382541, 2019). "Inactivating mutations in the genes encoding NKB (TAC3) and its cognate receptor, NK3R (TACR3), have also been recently shown, like GPR54 mutations, to result in hypogonadotropic hypogonadism; characterized by a failure to progress through puberty." (PMID 22377698, 2013). "Mutations associated with loss of TAC3/TACR3 gene functions cause IHH (isolated hypogonadotropic hypogonadism), characterized by a lack of sexual maturation and low circulating levels of LH and gonadal steroids." (PMID 32189110, 2020). "Moreover, mutations in the TAC3 and TACR3 genes were found to cause hypogonadotropic hypogonadism in humans, demonstrating that NKB and NK3R play a key role in the regulation of reproduction." (PMID 31906206, 2019).
Infertility (13 papers, 2013 to 2025). "The loss of TACR3 or NKB function in the human hypothalamus can lead to congenital gonadal dysplasia and infertility, indicating that human TACR3 plays an important role in reproductive function." (PMID 40361657, 2025). "Indeed, human genetic studies have associated loss of function mutations on either TAC3 or TACR3 genes (encoding NKB and its receptor NK3R respectively) with hypogonadism and infertility, similar to the phenotypes of Kiss1 or GPR54 mutants." (PMID 23543285, 2013). "Furthermore, we found that fadrozole permanently influenced the differentiation of secondary sexual characteristics and reproductive tissues, and we identified several candidate genes, such as SPEF2, DNAI1, and TACR3, that were related to infertility in sex-reversed chickens." (PMID 36617567, 2023). "We found that the structure of the gonads and sperm were greatly deformed, and we identified several promising genes related to spermatogenesis and infertility, such as SPEF2, DNAI1, and TACR3, through RNA-seq." (PMID 36617567, 2023).
Anxiety (9 papers, 2020 to 2025). Intense feelings of nervousness, tension, or panic often arise in response to interpersonal stresses. "This intriguing finding led us to look closely at the synaptic and molecular pathways that link TACR3 deficiency, anxiety, sex hormones and plasticity." (PMID 38135756, 2024). "The DG is associated with affective processing and innate anxiety, and TACR3 deficiency in rats provoked an increase in spine density and basal synaptic transmission in this structure." (PMID 38135756, 2024). "Indeed, in males, sexual development is associated with a substantial increase in hippocampal TACR3 expression, coinciding with elevated serum testosterone and a significant reduction in anxiety." (PMID 38135756, 2024). "Dysfunctional TACR3 has been associated with pubertal failure and anxiety, yet the mechanisms underlying this remain unclear." (PMID 38135756, 2024). "Hence, we have investigated the relationship between TACR3 expression, anxiety, sex hormones, and synaptic plasticity in a rat model, which indicated that severe anxiety is linked to dampened TACR3 expression in the ventral hippocampus." (PMID 38135756, 2024). "To summarize, our study proposes TACR3 as a critical link between LTP and anxiety, providing insights into the mechanisms underlying anxiety, and potential treatments for anxiety disorders involving testosterone and the induction of plasticity." (PMID 38135756, 2024). "Our study assessed how testosterone and other sex hormones influenced hippocampal TACR3 expression, revealing intricate interactions that potentially have ramifications for understanding anxiety-like behavior and synaptic plasticity." (PMID 38135756, 2024). "The present study sets out to explore the intricate connection between TACR3, testosterone, and anxiety, the latter a prominent phenotype observed in individuals with non-syndromic normosmic CHH." (PMID 38135756, 2024). "Considering the critical role of TACR3 in CHH, where patients experience lower testosterone levels and anxiety, we studied the expression of TACR3 during sexual maturation." (PMID 38135756, 2024). "These outcomes suggest that testosterone and TACR3 are related reciprocally, whereby they mutually influence each other to modulate anxiety-like behavior." (PMID 38135756, 2024). "This study focused on the intricate relationship between hippocampal TACR3 expression, plasticity-related signaling pathways, sex hormones, and anxiety-like behavior." (PMID 38135756, 2024). "The findings of this study shed light on the potential importance of hippocampal TACR3 in modulating anxiety, providing valuable insight into the intricate interplay between TACR3, sex hormones, and anxiety-related mechanisms." (PMID 38135756, 2024). "Gene expression profiles in the amygdala have identified and validated Ucn3 and Tacr3 genes to be involved in fear/anxiety traits in rats." (PMID 38516965, 2024). "In conclusion, our study provides valuable insights into the intricate interplay between TACR3, sex hormones, anxiety, and synaptic plasticity." (PMID 38135756, 2024). "Anxiolytic effects of TACR3 agonists and anxiogenic effects of TACR3 antagonists have already been reported, and TACR3 expression has been found to vary in the amygdala relative to the state of anxiety displayed by rats." (PMID 38135756, 2024). "These experiments were prompted by the observation of weaker TACR3 expression in the ventral hippocampus of rats exhibiting elevated anxiety (SA rats)." (PMID 38135756, 2024). "The findings highlight the pivotal role of TACR3 as a critical mediator between testosterone levels and anxiety-like behavior." (PMID 38135756, 2024). "Here, the role of tachykinin receptor 3 (NK3R) in the lateral habenula (LHb) in trigeminal neuralgia and in pain-associated anxiety was systematically investigated." (PMID 36756128, 2023).
Anxiety (continued). "It is worthwhile to undertake further experimental investigations to verify the role of Tacr3 in the LHb in allodynia and anxiety-like behaviors in TN." (PMID 32264959, 2020). "In conclusion, Tacr3 in the LHb plays a protective role in treating trigeminal nerve injury-induced allodynia and anxiety-like behaviors by suppressing the hyperexcitability of LHb neurons." (PMID 32264959, 2020). "Both the EPM and OFT suggested that the overexpression of Tacr3 in unilateral LHb neurons was enough to rescue nerve injury-induced anxiety-like behaviors." (PMID 32264959, 2020). "We hypothesized that rats with lower TACR3 expression in the hippocampus and lower serum testosterone levels would display heightened anxiety-like behavior in the EPM." (PMID 38135756, 2024). "Downregulation of TACR3 was observed in the lateral habenula of mice showing anxiety-like behaviors, whereas TACR3 overexpression in the same area significantly reversed such anxiety-like behaviors." (PMID 38135756, 2024). "Interestingly, male adolescent rats with lower testosterone levels display more intense anxiety-like behavior than adult males, while systemic testosterone administration increased hippocampal TACR3 expression." (PMID 38135756, 2024). "However, the significance of TACR3 in anxiety regulation has remained unexplored, particularly in the context of sex hormone function and at the molecular and synaptic levels." (PMID 38135756, 2024). "Notably, we demonstrate the modulatory effect of sex hormones on TACR3 expression and its reciprocal control over sex hormone levels and anxiety-like behavior." (PMID 38135756, 2024). "Tacr3 overexpression in the unilateral habenula significantly reduced anxiety-like behavior." (PMID 34276303, 2021). "We propose that Tacr3-targeted interventions might be worth pursuing for treating pain and anxiety in TN." (PMID 32264959, 2020). "Both the EPM and OFT showed that the overexpression of Tacr3 in bilateral LHb neurons could also reverse nerve injury-induced anxiety-like behaviors." (PMID 32264959, 2020). "Therefore, nerve injury-induced allodynia and anxiety-like behaviors are differentially modulated by the LHb, and selective inhibition of unilateral or bilateral LHb function by Tacr3-targeting methods is a promising treatment for pain and anxiety in TN patients." (PMID 32264959, 2020). "Moreover, Tacr3 overexpression could reverse the trigeminal nerve injury-induced allodynia and anxiety-like behaviors by inhibiting the hyperexcitability of LHb neurons." (PMID 32264959, 2020). "In our previous work, microarray analysis showed that the expression of Tacr3 was downregulated in the LHb of pT-ION mice, and we confirmed here that reversing the downregulation of Tacr3 in the bilateral LHb alleviated pT-ION-induced orofacial allodynia and pain-related anxiety-like behaviors." (PMID 36756128, 2023). "As we show in this study, chemogenetic inhibition of the release of NKB in the fPAG reversed the alleviating effect of Tacr3 overexpression on pT-ION-induced allodynia and anxiety-like behaviors, indicating that fPAGNKB → LHb regulates orofacial allodynia and anxiety-like behaviors in pT-ION mice." (PMID 36756128, 2023). "Here, we aimed to inhibit NKB+ neurons from releasing NKB from the fPAG to the LHb in order to test whether NKB release from the fPAG would affect the alleviating effect of Tacr3 overexpression in the LHb on pT-ION-induced allodynia and anxiety-like behavior." (PMID 36756128, 2023). "To test whether the downregulation of Tacr3 in the unilateral LHb was involved in pT-ION-induced allodynia and anxiety-like behaviors, we overexpressed Tacr3 by injecting AAV-Tacr3-Ove virus into the left LHb." (PMID 32264959, 2020). "Rescuing the downregulation of Tacr3 by AAV-mediated Tacr3 overexpression in the unilateral LHb significantly reversed pT-ION-induced anxiety-like behaviors but not allodynia." (PMID 32264959, 2020).
Anxiety (continued). "Moreover, not only anxiety-like behaviors, but also allodynia after pT-ION were significantly alleviated by chemicogenetic inhibition of bilateral LHb neurons or by bilateral Tacr3 overexpression in the LHb." (PMID 32264959, 2020). "Also, inhibition of the release of NKB from the fPAG reversed the alleviating effect of Tacr3 overexpression in the LHb on pT-ION-related anxiety-like behaviors in the EPM but not in the OFT." (PMID 36756128, 2023). "Functional blockade of glutamatergic neurons in the unilateral LHb was enough to alleviate pT-ION-induced anxiety-like behaviors but not allodynia, as was rescuing the pT-ION-induced downregulation of Tacr3, a gene enriched in the calcium signaling pathway." (PMID 32264959, 2020).
cocaine dependence (6 papers, 2014 to 2022). A psychologically and socially impaired state, with or without physiological changes, that develops as a result of using cocaine and which leads to compulsive behaviors to acquire the substance. "The particular ligand/receptor system NKB/NK3R, (encoded by TAC3/TACR3), previously investigated only for preeclampsia, alcohol, and cocaine dependence, gained an increasingly important role in human reproductive axis and in CHH onset in the last seven years." (PMID 25254043, 2014). "Interestingly, genetic polymorphisms in TACR3 have been previously associated with alcohol and cocaine addiction, and hypomethylation of the promoter region in blood is linked to repeated cocaine administration in marmoset monkeys." (PMID 36581877, 2022). "The sequence variations in tachykinin receptor 3 are associated with alcohol and cocaine addiction." (PMID 31417344, 2019). "Single nucleotide polymorphisms in Tacr3 have been associated with alcohol and cocaine dependence in humans, and thus genetic variation may also play a role in methamphetamine addiction." (PMID 26188473, 2015). "Certain additional TACR3 polymorphisms, such as A29V, G59E, S455G, A449S, W275X, and rs4580655, have been associated with idiopathic central pubertal disorders, predicting and improving learning and memory in aged organism, alcohol and cocaine dependence, and pediatric slow transit constipation." (PMID 27347521, 2015). "There have been no previous studies in the literature reporting association or not of rs3733631 TACR3 gene polymorphism with rosacea; however, it has been studied in alcohol and cocaine dependence." (PMID 27347521, 2015). "Interestingly, stimulation of these receptors has been shown to reduce alcohol drinking, without impacting food or water intake and SNPs in Tacr3 gene are linked in alcohol and cocaine dependence." (PMID 31717954, 2019).